IL18 (interleukin 18)
Diseases named in the same sentence as IL18 in open-access papers (continued):
Sharing a sentence is not in itself a finding about the gene and the disease.
synovitis (5 papers, 2021 to 2025). Inflammation of a synovial membrane. "IL-4, IL-18, IL-7, and IL-12 represent effector cell function and are involved in the perpetuation of synovitis and chronic synovitis." (PMID 38675400, 2024). "Our findings demonstrate that treatment with JTQBG significantly reduces the levels of IL-1β and IL-18, suggesting its potential involvement in regulating the NF-κB signaling pathway in synovitis." (PMID 38545550, 2024). "It is noteworthy that the combined effect of mitophagy and pyroptosis leads to inflammatory changes in synovial fibroblasts (FLS), and through the continuous secretion of inflammatory factors such as IL-1β and IL-18 ultimately promotes the progression of synovitis." (PMID 40728955, 2025). "In animal experiments, the topical application of SP-NEs gel paste can effectively reduce synovitis of KOA rats and downregulate the gene and protein expressions of IL-1β, IL-18, and TRPA1." (PMID 34876884, 2021).
Ureteral obstruction (5 papers, 2014 to 2023). Obstruction of the flow of urine through the ureter. "IL-18 is associated with renal interstitial fibrosis, and IL-18 neutralization has been shown to prevent renal injury and fibrosis in unilateral ureteral obstruction (UUO) mice." (PMID 33344483, 2020). "Fas ligand-mediated cell death is also IL-18-dependent, and IL-18 neutralization is associated with a reduction in renal tubular apoptosis in unilateral ureteric obstruction (UUO) and I-R injury." (PMID 24450291, 2014). "A study showed that the expression of IL-1β, IL-6, IL-18, and TNF-α in peripheral blood and renal tissues of rats with unilateral ureteral obstruction was significantly reduced by DSF." (PMID 35563653, 2022). "For instance, reduced expression and maturation of IL-1β, IL-18 and caspase-1 activation and reduced tubular damage and fibrosis in an NLRP3 knockout unilateral ureteral obstruction (UUO) model was observed." (PMID 34680443, 2021). "mRNA expression of IL1α, IL1β and IL18 but not of TNFα increased in response to ureteral obstruction (D and C correspondingly)." (PMID 37553369, 2023).
visceral leishmaniasis (5 papers, 2010 to 2025). A severe form of leishmaniasis characterized by irregular bouts of fever, substantial weight loss, swelling of the spleen and liver, and anemia (which may be serious). "Mice deficient in IL-18 exhibit significantly higher parasite burdens following infection with L. donovani, indicating a critical role for IL-18 in controlling visceral leishmaniasis." (PMID 40794782, 2025). "Moreover, the IL-18 cytokine presents a protective effect against visceral leishmaniasis caused by L. infantum infection in humans, inducing IFN-γ and leading to the production of Th1 responses and natural killer (NK) cells." (PMID 36759910, 2023). "Lower plasma level of IL-18 in visceral leishmaniasis (VL) patients might be associated with polymorphisms in the regulating or coding region of the gene." (PMID 25405235, 2014). "We conclude that IL-15 is not functioning as a universal NK-cell priming signal and that IL-18 contributes to the NK-cell response in visceral leishmaniasis." (PMID 20213736, 2010). "In conclusion, our analysis of the early NK-cell effector response in visceral leishmaniasis revealed differential functions for the cytokines IL-12, IL-15 and IL-18." (PMID 20213736, 2010). "The IL-18-independent effect of IL-12 on NK-cell activation in visceral leishmaniasis might result from an increased nuclear translocation of STAT4 and/or NF-κB as previously seen in NK cells present in unseparated mouse macrophage populations 36,37." (PMID 20213736, 2010). "(ii) Is IL-18 similar to IL-12 a prerequisite for NK-cell activation in visceral leishmaniasis?" (PMID 20213736, 2010). "As IL-18 is known to activate mouse NK cells in vitro and in vivo, we tested whether IL-18 contributes to the NK-cell activation in visceral leishmaniasis." (PMID 20213736, 2010). "In the context of L. infantum-induced visceral leishmaniasis, we assessed immune mediators including TNF, IL-1β, CXCL10, IL-12p70, IL-18, IL-23, and C-C motif chemokine ligand 2 (CCL2)." (PMID 40794782, 2025). "The IL-18, known as IFN-γ inducing factor, increases the production of this interferon by T cells and has a relevant role in the defence against visceral leishmaniasis." (PMID 36759910, 2023). "Our data clearly illustrate that the full induction of NK-cell effector functions in visceral leishmaniasis requires IL-12 and IL-18, but – unexpectedly – is entirely independent of IL-15." (PMID 20213736, 2010). "We therefore performed experiments to define how IL-18 might promote the IFN-γ production and the cytotoxicity of NK cells in visceral leishmaniasis." (PMID 20213736, 2010).
acute lymphoblastic leukemia (4 papers, 2017 to 2025). Leukemia with an acute onset, characterized by the presence of lymphoblasts in the bone marrow and the peripheral blood. "Additionally, humanized mice with patient-derived xenografts from acute lymphoblastic leukemia (ALL) were used to highlight the critical roles of GM-CSF, IL-18, MIP-1α, and IP-10 in the CAR-T response." (PMID 39594640, 2024). "We have previously shown that FAB subgroups M4 and M5 are characterized by the highest LDL degradation rate compared to FAB-M1-3 and acute lymphoblastic leukemia which is in agreement with reports showing that TNF-α, IL-6, IL-8, and IL-18 are over-expressed and secreted in these subgroups." (PMID 28488049, 2017).
Airway obstruction (4 papers, 2015 to 2025). Obstruction of conducting airways of the lung. "As a pro-inflammatory and pro-apoptotic cytokine, IL-18 is expressed primarily in alveolar macrophages and bronchial and alveolar epithelial cells, promoting airway obstruction and inflammatory responses by activating and migrating inflammatory cells." (PMID 40761855, 2025). "In a murine model, intraperitoneal IL-18 injection increased eosinophil recruitment into the airways, and intranasal rIL-18 administration also transformed CD274-eosinophils to CD274+ pathogenic eosinophils that were shown to promote mucus hypersecretion and airway obstruction." (PMID 39554494, 2024). "IL-18 may indirectly affect airway obstruction by contributing to mechanisms of mucus plugging." (PMID 39554494, 2024).
alcoholic hepatitis (4 papers, 2017 to 2024). Acute hepatitis resulting from ingestion of alcohol. "CASP4 and IL-18 are both involved in the pathogenesis of alcoholic hepatitis (AH) but has opposite effects in the pathogenesis." (PMID 35785176, 2022). "In patients with alcoholic hepatitis, there were observed increasing levels of TNF-α, IL-6, IL-8, and IL-18 pro-inflammatory cytokines." (PMID 38473721, 2024).
alcoholic liver diseases (4 papers, 2012 to 2026). A disorder caused by damage to the liver parenchyma due to alcohol consumption. "Notably, increased expression of inflammasome components (IL‐1β, IL‐18, Casp1) has been documented in patients with alcoholic liver disease and is associated with hepatic injury." (PMID 41583017, 2026). "The present study demonstrates that chronic alcohol feeding reduces IL-18 and administration of IL-18 restores intestinal IFN-γ levels (but not IL-22), reverses alcohol-reduced AMP expression, and alleviates alcoholic liver damage." (PMID 33536944, 2020).
amyloid (4 papers, 2010 to 2025). "A chronic state of inflammation caused by cytokines like IL-6, IL-18, and TNF-α represents a major link to the formation of increased amyloid plaques and tau tangles." (PMID 41280310, 2025). "Emerging research focuses on epigenetic regulation of MEFV, potential biomarkers of disease activity (such as SAA or interleukin-18 levels), and “treat-to-target” strategies that aim to suppress subclinical inflammation and prevent amyloidosis." (PMID 41523473, 2025). "In these brains IL-18 was found in microglia, astrocytes and in neurons that co-localize with amyloid-β-plaques and with tau, suggesting that amyloid-β may induce the synthesis of IL-18, and IL-18 kinases involved in tau phosphorylation as a part of the amyloid-associated inflammatory reaction." (PMID 20113500, 2010).
amyotrophic lateral sclerosis (4 papers, 2018 to 2024). Amyotrophic lateral sclerosis (ALS) is a neurodegenerative disease characterized by progressive muscular paralysis reflecting degeneration of motor neurons in the primary motor cortex, corticospinal tracts, brainstem and spinal cord. "Similarly, other research teams have reported increases in the expression and activity of NLRP3, IL-1β, IL-18 and caspase-1 in plaques of MS patients and the tissues of amyotrophic lateral sclerosis (ALS) (or motor neurone disease) patients." (PMID 29052145, 2018). "The elevated formation of inflammasomes, expression of IL-1β and IL-18, and excessive cleavage of GSDMD have been reported in amyotrophic lateral sclerosis (ALS) and multiple sclerosis (MS) cases, indicating a crucial role for pyroptosis in the neuroinflammation and development of ALS." (PMID 39337436, 2024).
ANCA-associated vasculitis (4 papers, 2012 to 2024). "Higher levels of IL-18 have also been measured in patients with ANCA-associated vasculitis and those undergoing hemodialysis." (PMID 32297262, 2020). "Studies have shown that in ANCA-associated vasculitis, the level of IL-18 may increase, which may be due to the activation of immune cells during the inflammatory process leading to the release of IL-18." (PMID 38415205, 2024). "In patients with ANCA-associated vasculitis (AAV), the serum level of IL-18 was elevated and the tissue protein content of NOD2, NLRP3, and NLRC5 was higher than that in healthy controls, demonstrating the role of the inflammasome in these disorders." (PMID 38020086, 2023).
Anorexia (4 papers, 2010 to 2024). Lack of desire to eat (loss of appetite). "The data showed that exposure to DON and its congeners at 2.5 mg/kg BW significantly elevated plasma IL-18 and IL-6 levels associated with toxin-induced anorexia." (PMID 39691381, 2024). "Moreover, the temporal relationship between the expression of IL-18 and IL-6 was consistent with the anorexia caused by these mycotoxins." (PMID 39691381, 2024). "Inflammatory cytokines IL-18 and IL-6 can further activate the NF-κB signaling pathway, regulating POMC activity to cause anorexia." (PMID 39691381, 2024). "Pro-inflammatory cytokines, e.g., interleukin-1 β (IL-1β), IL-6, interleukin-18 (IL-18), and TNF, induce topical and systemic inflammation causing anorexia and fever." (PMID 36992177, 2023). "A number of cytokines have been previously linked to anorexia, including IL-6, TNF-α, CXCL8, IL-1β, IL-18, IL-2, and IFN-γ." (PMID 32071269, 2020). "In order to investigate the potential roles of pro-inflammatory cytokines IL-18 and IL-6 in anorexia induction, mice were exposed with a common anorexigenic dose of 2.5 mg/kg BW DON, 3-ADON, 15-ADON, NIV and FX by two methods (IP vs. oral) using a previously established mouse anorexia model." (PMID 39691381, 2024). "In addition, the temporal relationship of DON and its congeners-induced IL-18, as well as IL-6 expression, was found to be consistent with their resulting anorexia." (PMID 39691381, 2024). "The mechanisms through which IL-18 exerts these effects are largely unknown but central action was proposed following the observation that i.c.v. injections of exogenous IL-18 induces sleep and anorexia." (PMID 20113500, 2010). "Moreover, we speculate that IL-18 and IL-6 in the toxin-induced anorexia response directly acts on the hypothalamus to regulate the appetite center." (PMID 39691381, 2024). "Based on this, we hypothesized that the expression of inflammatory cytokines (IL-18, IL-6) induced by DON and its congeners may lead to anorexia by altering the composition of the intestinal flora and consequently." (PMID 39691381, 2024). "In this study, we focused on two common pro-inflammatory cytokines (IL-18, IL-6), and investigated the anorexigenic potency of DON and its congeners and the release of IL-18 and IL-6 in plasma under different methods (oral vs. IP) based on anorexia models in mice." (PMID 39691381, 2024). "However, whether IL-18 and IL-6 are involved in the anorexia induced by DON and its congeners is not clear." (PMID 39691381, 2024).
autoimmune uveitis (4 papers, 2019 to 2024). An autoimmune form of uveitis (disease). "This also promoted reduction in SE-related Th1 gene expression (e.g. Ifng, Tnf, Fasl, IL18 and Ctla4), which caused disease remission in autoimmune uveitis mice." (PMID 35514959, 2022). "It is worth noting that IL-2, IL-6, IL-13, IL-18, IFN-γ, and TNF-α were significantly higher in the aqueous humor of children with JIA-associated autoimmune uveitis." (PMID 36969183, 2023). "Previous studies have shown that the primary function of retinal microglia in autoimmune uveitis is to initiate the disease, and without microglia, no local inflammation would develop; moreover, microglia produce cytokines such as IL-1β and IL-18 by the activation of inflammasomes." (PMID 38802924, 2024).
babesiosis (4 papers, 2018 to 2025). Babesiosis refers to a condition caused by microscopic parasites that infect the red blood cells. "The response of PBMCs from adult cattle during the acute phase of the babesiosis at 10 dpi showed upregulation of the pro-inflammatory cytokines IL-1β, TNFα and IL-18." (PMID 41398915, 2025). "It seems probable that in this disease, as in bovine babesiosis, early increased production of IL-18 and IL-12 stimulates the release of IFN-γ and TNF-α, leading to activation of iNOS and NO production, which together with delayed secretion of IL-10 causes oxidative damage to erythrocytes." (PMID 36839438, 2023).
benign prostatic hyperplasia (4 papers, 2015 to 2026). A non-cancerous nodular enlargement of the prostate gland. "Nuclear factor kappa B (NF-κB) subunits p65 and p50, along with the cytokines IL-18 and IL-10, are central mediators of inflammation, but remain understudied in the context of benign prostatic hyperplasia (BPH) and occupation-related risks." (PMID 41569207, 2026). "The correlation analysis showed a relationship between the amount and intensity of the IL-18 expression in the benign prostatic hyperplasia tissue and the percentage of SCFAs isolated from the stool of patients." (PMID 37847180, 2023). "There is mounting evidence to support the role of inflammation in benign prostate hyperplasia (BPH), and a recent study reported expression of inflammasome derived cytokine IL-18 in prostate biopsy of BPH patients." (PMID 25991911, 2015). "Our study also found a negative correlation between the overall percentage of IL-18 (+) cells in the glandular epithelium of benign prostatic hyperplasia tissue in the group of patients with MetS and the amount of acetic acid in the faeces." (PMID 37847180, 2023).
brucellosis (4 papers, 2019 to 2024). Brucellosis is a bacterial infection that spreads from animals to people via unpasteurized dairy products or by exposure to contaminated animal products or infected animals. "Furthermore, acute brucellosis was associated with significantly higher serum IL-18 levels." (PMID 39100670, 2024). "Cytokines (IL-18, IFN-γ) associated with inflammasome changes are also altered at different stages of brucellosis." (PMID 36068262, 2022). "The expression of the NLRP3 receptor gene in patients with acute brucellosis negatively correlates with IL-18 expression (r = − 0.454 and P = 0.044)." (PMID 36068262, 2022). "Additionally, AIM2 positively correlates with IL-18 expression in acute brucellosis patients and IFN-γ expression in chronic brucellosis patients." (PMID 36068262, 2022). "Serum IL-18 and IFN-γ levels were significantly higher in patients with acute brucellosis than in healthy controls." (PMID 36068262, 2022).
cardiac arrest (4 papers, 2015 to 2024). Cessation of breathing and/or cardiac function. "“Cardiac arrest group” skin was associated with elevated levels of caspase-1 and IL-18." (PMID 26635801, 2015). "The results from qRT-PCR and Western blotting showed that MCC950 significantly suppressed the levels of NLRP3, ASC, IL-1β, and IL-18 at 12 h after cardiac arrest, in both hippocampus and cortex." (PMID 32703306, 2020). "We found that the mRNA levels coding for IL-1β and IL-18 in hippocampus and cortex of post-cardiac arrest rats were downregulated after treatment with Ac-YVAD-cmk." (PMID 32703306, 2020). "In skin, the levels of IL-18 and IL-1α present in “cardiac arrest group” animals were much higher than those seen in any other groups." (PMID 26635801, 2015). "The only cytokine elevated differentially between groups within muscle tissue was IL-18, whose expression was considerably higher in “cardiac arrest group” animals." (PMID 26635801, 2015). "In muscle, similar differences between “cardiac arrest group” animals and “injury group” were also seen, along with marked increases in IL-18, IL-1α, IL-6, IFNγ, and MCP-1." (PMID 26635801, 2015). "In “cardiac arrest group” muscle, IL-18 levels were also markedly increased; however, caspase-1 levels were lower than in “injury group” muscle." (PMID 26635801, 2015). "Consistent with this hypothesis, our data demonstrate that there is indeed intensive pyroptosis and increased caspase-1 activity in the activated microglia population after cardiac arrest, along with elevated levels of IL-1β and IL-18." (PMID 32703306, 2020). "Notably, IL-1α and IL-18, along with caspase-1, were greatly elevated in the skin following cardiac arrest, consistent with differential inflammasome activation." (PMID 26635801, 2015). "Cardiac arrest greatly elevates IL-1α, IL-18, and caspase-1 in the skin." (PMID 26635801, 2015). "Cardiac arrest and ECPR markedly increased the plasma levels of IL-10, VEGF, leptin, TNF-α, IL-1β, IL-6, fractalkine, IL-5, IL-18, IP-10, IL-4, eotaxin, MIP-1α, IL-17α, IL-12, RANTES, G-CSF, LIX, and MCP-1." (PMID 34781966, 2021). "Moreover, the delivery of MCC950 led to a significant reduction in the number of CD45high CD11b+ cells accompanied by the inhibition of IL-1β and IL-18, suggesting that the intervention of NLRP3 by MCC950 prevents the post-cardiac arrest inflammatory response." (PMID 32703306, 2020). "The presence of IL-18 and IL-1β led us to hypothesize the presence and activation of the NLRP3 inflammasome in response to localized tissue injury and cardiac arrest." (PMID 26635801, 2015).
carotid atherosclerosis (4 papers, 2017 to 2024). A thickening and loss of elasticity of the walls of carotid arteries that occur with formation of atherosclerotic plaques. "Surprisingly, the carotid artery specimen revealed a decreased expression of HMGB1 and S100B with a concomitant increase in the pro-inflammatory cytokines IL-17, IL-18 and IL-1β suggesting the priming role of DAMPs in initiating carotid atherosclerosis." (PMID 35531433, 2022). "GSDMD, CASP1, NLRC4, AIM2, and IL18 were the key pyroptosis related genes, which might provide a new sight in the prevention of fatal strokes in advanced carotid atherosclerosis." (PMID 38167983, 2024). "Because little is known about the NLRP3 inflammasome, IL-1β and IL-18 in patients with T2DM and AS, here we performed a cross-sectional study investigating these inflammatory components in patients with T2DM complicated with carotid atherosclerosis (CAS)." (PMID 29151018, 2017).
cholestasis (4 papers, 2015 to 2021). Impairment of the bile flow caused by obstruction within the liver, or outside the liver in the bile duct system. "IL-18 was reported to be significantly elevated in patients with obstructive jaundice and other diseases associated with cholestasis, such as primary biliary cirrhosis and intrahepatic cholestasis of pregnancy." (PMID 26292095, 2015).